SMARCA4 (SWI/SNF related BAF chromatin remodeling complex subunit ATPase 4)
Diseases named in the same sentence as SMARCA4 in open-access papers (continued):
Sharing a sentence is not in itself a finding about the gene and the disease.
ovarian carcinoma (47 papers, 2011 to 2026). A malignant neoplasm originating from the surface ovarian epithelium. "SMARCA4-deficient lung and ovarian cancer cells show increased sensitivity to the KDM6 inhibitor GSK-J4, which can be an effective treatment option after cisplatin resistance." (PMID 41170461, 2025). "Together, these data establish that SMARCA4/2-deficient ovarian cancer cells exhibit reduced glycolysis and highly depend on OXPHOS." (PMID 37210563, 2023). "The more common ovarian cancer subtype, high-grade serous ovarian cancer, rarely harbor SMARCA4 mutations (<1% in both age groups)." (PMID 36433963, 2022). "This difference led to an overall SMARCA4 mutation rate of 8% in AYAs and 2% in OAs with ovarian cancer." (PMID 36433963, 2022). "SMARCA4 mutation was associated with sensitivity to four FLT1 (VEGFR1) inhibitors in ovarian cancer cells, including axitinib, foretinib, pazopanib and sorafenib." (PMID 36180906, 2022). "There are also in vitro and in vivo data on susceptibility to CDK4/6 inhibitors and ICIs in SMARCA4-loss ovarian cancer." (PMID 36431263, 2022). "Other SWI/SNF altered cancers that are dependent on EZH2 include SS18-SSX translocated synovial sarcoma, ARID1A-mutated ovarian cancer, SMARCA4-mutated lung and ovarian cancers, and PBRM1-mutated renal cancers." (PMID 34617019, 2021). "We recently uncovered that SMARCA4 loss in an ovarian cancer subtype causes cyclin D1 deficiency leading to susceptibility to CDK4/6 inhibition." (PMID 30718506, 2019). "Here we show that the switch of the SWI/SNF catalytic subunits from SMARCA4 to SMARCA2 drives resistance to EZH2 inhibitors in ARID1A-mutated ovarian cancer cells." (PMID 30297712, 2018). "Here, the authors demonstrate that the switch of the SWI/SNF catalytic subunits from SMARCA4 to SMARCA2 drives resistance to EZH2 inhibitors in ARID1A-mutated ovarian cancer cells." (PMID 30297712, 2018). "Rare ovarian cancers would benefit from expanded mutation profiling to identify additional potential targets as well as confirm the presence of SMARCA4 in SCCO-HT." (PMID 27566252, 2016). "Overall, our results indicate that SMARCA4 inhibitors could be used to enhance immune responses in the context of ovarian cancer and potentially other senescence-associated diseases." (PMID 39813356, 2025). "These unbiased observations suggest that SMARCA4/2-deficient ovarian cancer cells may rely on OXPHOS more than glycolysis for energy supply." (PMID 37210563, 2023). "Accordingly, glucose uptake capacities of SMARCA4/2-deficient ovarian cancer cells were strongly reduced, consistent with their markedly low GLUT1 protein abundance compared to controls (left); ectopic expression of GLUT1 in SMARCA4/2-deficient cells significantly increased glucose uptake." (PMID 37210563, 2023). "Recently, we and others have demonstrated that SMARCA4/2-deficient ovarian cancers rely on epigenetic reprogramming and are responsive to inhibitors targeting the polycomb repressive complex 2, histone deacetylases, and the bromodomain-containing protein 427–30." (PMID 37210563, 2023). "In SMARCA4-loss ovarian cancer cells, tazemetostat (EZH2 inhibitor) showed a potential benefit." (PMID 36431263, 2022). "In addition to ESCC cell models, SMARCA2-deficient colorectal, pancreas and ovarian carcinoma cell lines display SMARCA4 dependency, indicating that the interdependence of SMARCA2 and SMARCA4 is hard-wired and context-independent." (PMID 31406271, 2019). "Our further research showed that USP28/SOX9 modulate the HRR activity of ovarian cancer by regulating SMARCA4, UIMC1, and SLX4 expression." (PMID 40240356, 2025). "SMARCA4 inhibition enhances NK-mediated killing of senescent cells and can be combined with cisplatin to treat ovarian cancer." (PMID 39813356, 2025).
ovarian carcinoma (continued). "We profiled OXPHOS and glycolysis capacities in SMARCA4/2-deficient ovarian cancer cells (BIN-67, SCCOHT-1, COV434, TOV-112D) and SMARCA4/2-proficient high-grade serous ovarian carcinoma (HGSOC) cells (OVCAR3, OVCAR4, OVCAR5, CaOV3)." (PMID 37210563, 2023). "These therapies target either the enhanced proliferative capacity of ovarian cancer cells caused by mutations in ARID1A and SMARCA4 or directly promote apoptosis of the tumour cells to achieve therapeutic goals." (PMID 36883311, 2023). "Ovarian cancer cell A2780 with ARID1A-deificiency and pancreatic cancer cell Hs700T with SMARCA4-deficiency were also moderately sensitive to MAK683." (PMID 35169119, 2022). "Promotion of HR repair is facilitated by SMARCA4 and in the ovary, alterations in SMARC4 have been associated with ovarian carcinomas." (PMID 36214631, 2022). "Second, we found that lung or ovarian cancer cells with inactivated SMARCA4 not only were refractory to the growth suppression triggered by SAHA, but also aberrantly accumulated H3K27me3 following the administration of this inhibitor." (PMID 34262032, 2021). "OVCAR4, an ovarian carcinoma-derived cell line which is SMARCA4-proficient, was also included as an additional control." (PMID 30718512, 2019). "Differences between ovarian cancer cells and cells derived from SCCOHT have been previously reported by a mutation in the SMARCA4 gene as a potential marker for the SCCOHT." (PMID 25103190, 2014). "Western blot analysis of BRG-1 as the protein product of the SMARCA4 gene revealed a pronounced expression in the NIH:OVCAR-3 and SK-OV-3 ovarian cancer cells, however, little if any BRG-1 protein was detectable in SCCOHT-1 cells." (PMID 25103190, 2014). "EZH2 and SMARCA4 are likely candidates to beassociated with ovarian cancer since they are amplified and/or overexpressed in anumber of cancers including prostate, gastric, and breast." (PMID 21423607, 2011). "Our results indicate that SMARCA4 inhibitors enhance NK-mediated surveillance of senescent cells and may represent senotherapeutic interventions for ovarian cancer." (PMID 39813356, 2025). "In addition to these genes, a high risk for ovarian cancer is associated with mutations in the DICER1, VHL, PTCH1, SUFU, SMARCB1, and SMARCA4 genes." (PMID 37685988, 2023). "Notably, epigenetic modifiers frequently showed more mutations in AYAs, including H3F3A, KDM5A and IDH1/2 in glioma, EP300 in liver cancer, SMARCA4 in ovarian cancer, and MEN1 in pancreatic cancer." (PMID 36433963, 2022). "SMARCA4 is commonly inactivated in lung and ovarian cancers." (PMID 34262032, 2021). "The high prevalence of SWI/SNF mutations in various human malignancies, the occurrence of SMARCA4 as the driver mutation in SCCOHT and the potential therapeutic strategy of EZH2 inhibitors led us to explore the role of SMARCA4 and EZH2 in epithelial ovarian cancers." (PMID 33230143, 2020). "This evidence suggests that SMARCA4 T910M might play similar roles in MB and ovarian carcinoma development." (PMID 31996670, 2020). "The ovarian cancers are characterized by reduced SMARCA4 gene expression and/or reduced protein function and, consequently, they are sensitive to growth and/or survival inhibition by one or more compounds that restore SMARCA4 gene expression and/or protein function." (PMID 31676783, 2019). "In addition to SMARCB1, other SWI/SNF subunits are often mutated in cancer like ARID1A in ovarian carcinoma, SMARCA4 (also known as BRG1) in lung and pancreas cancer, and PBRM1 in renal cancer." (PMID 27222667, 2016). "Moreover, tubulinβ3 expression in SMARCA4/BRG1-defective SCCOHT-1 in contrast to other ovarian cancer cells was also affected during chemotherapy treatment." (PMID 25103190, 2014). "This is particularly relevant for SMARCA4 which is mutatedin many cancer cell lines as well as patient samples but was not significantlyoverexpressed at a protein level in ovarian cancer compared to normal tissues." (PMID 21423607, 2011).
ovarian carcinoma (continued). "Finally, a recent study clarified that SMARCA4 T910M contributes to the targeting of SWI/SNF complexes on chromatin in ovarian carcinoma cells and that could influence CDKN2B expression." (PMID 31996670, 2020). "We observed that olaparib promotes the expression of SMARCA4, UIMC1, and SLX4 in ovarian cancer cells." (PMID 40240356, 2025). "In conclusion, these findings suggested that USP28/SOX9 positively regulates the expression of DDR genes (SMARCA4, UIMC1, and SLX4) by binding to their promoters in ovarian cancer cells." (PMID 40240356, 2025). "ChIP-Seq analysis revealed that SOX9 binds to the promoters of key DNA damage repair (DDR) genes (SMARCA4, UIMC1, and SLX4), thereby regulating DDR processes in ovarian cancer." (PMID 40240356, 2025). "For instance, SMARCA4, a subunit of the SWI/SNF chromatin remodeling complex, and FLT1 (VEGFR1) were identified as a CSL interaction in ovarian cancer cells." (PMID 36180906, 2022). "SMARCA4 and EZH2 expression was assessed by RT-PCR in 238 epithelial ovarian cancers (OCs) and put in relation to clinico-pathological parameters and patients’ outcome." (PMID 33230143, 2020). "Moreover, a PROTAC targeting SMARCA4 synergized with cisplatin to increase the infiltration of CD8 T cells and mature, activated NK cells in an immunocompetent model of ovarian cancer." (PMID 39813356, 2025). "Therefore, unlike SMARCA4-mutant NSCLC cells with intact SMARCA238, the OXPHOS dependency in SMARCA4/2-deficient ovarian cancer cells is not due to increased OXPHOS activity, but rather attributed to repressed glycolysis." (PMID 37210563, 2023). "By contrast, some well known ovarian cancer genes whose expression was not altered, such as VEGF, ERK, MAPK, TGF-β, and SMARCA4, displayed centralized placement in these same network maps, indicating high connectivity within the gene networks." (PMID 27788148, 2016).
thoracic tumors (46 papers, 2020 to 2026). "SMARCA4‐deficient undifferentiated thoracic tumors primarily affect younger adults, predominantly males, often with a history of smoking." (PMID 41577374, 2026). "In 2017, SMARCA4‐deficient thoracic tumor was identified as a distinct entity characterized by aggressive behavior, rapid growth, early metastasis, and poor prognosis." (PMID 41577374, 2026). "SMARCA4-deficient undifferentiated tumor (SMARCA4-UT) has emerged as a rare subtype of thoracic tumor, whose prognosis is unfavorable and for which standard therapeutic regimen is presently unavailable." (PMID 41261718, 2025). "SMARCA4-deficient thoracic tumors are currently divided into two main categories: SMARCA4-dNSCLC and SMARCA4-deficient undifferentiated carcinoma." (PMID 40313929, 2025). "The use of immunotherapy in SMARCA4-deficient undifferentiated thoracic tumors is recommended as a first-line, second-line, or later treatment depending on the expression of PD-L1." (PMID 39888726, 2025). "Clinicians should maintain a high index of suspicion for SMARCA4 deficiency in male smokers presenting with undifferentiated thoracic tumors but also broaden differential diagnoses to include SMARCA4-altered disease in extrapulmonary sites." (PMID 40867304, 2025). "In the fifth edition of the WHO classification (2021), a new category of thoracic tumors, thoracic SMARCA4-deficient undifferentiated tumors, was introduced." (PMID 40012963, 2025). "Thoracic SMARCA4-deficient tumors were first included in the World Health Organization’s (WHO's) 2015 classification of thoracic neoplasms as a distinct category to facilitate tailored therapeutic approaches." (PMID 39886719, 2024). "Most previous studies in this field have focused on SMARCA4‐deficient thoracic tumors or NSCLC, whereas our study explored the potential value of SMARCA4 as a prognostic marker in LUAD, which has clear innovative and clinical application value." (PMID 39322625, 2024). "In 2021, a new WHO classification of thoracic tumors of pulmonary epithelial origin is defined as SMARCA4-deficient undifferentiated tumor (SMARCA4-UT), which has distinct histopathological features and loss-of-function genomic alterations of the SMARCA4 gene." (PMID 39001412, 2024). "SMARCA4-deficient undifferentiated thoracic tumor (SMARCA4-UT) is a rare malignant tumor characterized by inactivation of the SMARCA4 gene and the presence of undifferentiated or rhabdoid morphology in the tissue." (PMID 38903719, 2024). "SMARCA4-deficient undifferentiated thoracic tumor (SMARCA4-UT) is characterised by inactivating mutation of SMARCA4 gene along with undifferentiated or rhabdoid morphology." (PMID 38347129, 2024). "SMARCA4-deficient (BRG-1 deficient) primary thoracic tumors are rare aggressive malignancies associated with poor prognosis." (PMID 39777351, 2024). "In 2021, the name was changed to SMARCA4-deficient undifferentiated tumors (SMARCA4-UTs) according to the WHO classification of thoracic tumors, to incorporate the findings of more recent studies." (PMID 39886719, 2024). "The objective of this publication was to explore SMARCA4-deficient undifferentiated thoracic tumors, other related SMARCA4-deficient tumors, and their overall pattern of presentation." (PMID 38390699, 2024). "The 5th edition of the 2021 World Health Organization (WHO) classification of thoracic tumors defines thoracic SMARCA4-deficient undifferentiated tumor (SMARCA4-UT) as a new entity of rare malignant tumor with an aggressive clinical course." (PMID 38374950, 2024). "Recent clinical research increasingly focuses on the clinical characteristics, molecular phenotypes, and therapeutic approaches of SMARCA4-deficient thoracic tumors." (PMID 39465834, 2024). "This study confirms that patients with advanced SMARCA4‐deficient thoracic tumors are predominantly male, with mean age of 64.6 years and history of heavy smoking." (PMID 38124509, 2023).
thoracic tumors (continued). "This study, centering on advanced SMARCA4‐deficient thoracic tumors, sought to delineate their clinical, pathological, immunohistochemical, and genetic attributes." (PMID 38124509, 2023). "The majority of patients with SMARCA4‐deficient thoracic tumors were heavy‐smoking males, averaging 64.6 years in age." (PMID 38124509, 2023). "SMARCA4‐deficient thoracic tumors, characterized by distinct clinicopathological, morphological, immunohistochemical, and genetic features, differ significantly from conventional non‐small‐cell lung carcinomas (NSCLCs)." (PMID 38124509, 2023). "Medical records of 36 patients diagnosed with stage IIIB, IIIC, or IV SMARCA4‐deficient thoracic tumors were analyzed." (PMID 38124509, 2023). "Another thoracic tumor harboring genetic alterations and protein aberrant expression of SMARCA4 is SMARCA4-deficient undifferentiated tumor (SD-UT), a recently recognized entity." (PMID 37115272, 2023). "SMARCA4‐deficient thoracic tumors exhibit distinct characteristics from conventional NSCLCs, and PD‐1 inhibitors show promise in treating advanced SMARCA4‐deficient thoracic tumors." (PMID 38124509, 2023). "The limited NGS panel potentially restricted a comprehensive understanding of the genetic features of SMARCA4‐deficient thoracic tumors." (PMID 38124509, 2023). "Despite the typically poor prognosis for patients with SMARCA4‐deficient thoracic tumors, these findings offer promising avenues for treatment." (PMID 38124509, 2023). "In version 2021 of the WHO classification of thoracic tumors, thoracic SMARCA4‐deficient undifferentiated tumors (SMARCA4‐UT) were mentioned in the pulmonary epithelial tumor section, refocusing attention on SMARCA4." (PMID 37184108, 2023). "This study identified 36 patients with advanced SMARCA4‐deficient thoracic tumors using IHC during routine clinical practice." (PMID 38124509, 2023). "Less frequent, but possible challenging diagnosis constitute lymphomas, SMARCA4‐deficient thoracic tumors, desmoplastic small round cell tumor, monophasic synovial sarcoma, and CIC‐translocated sarcomas." (PMID 36808895, 2023). "The absence of actionable mutations limited available treatment options and potential benefit of tyrosine kinase inhibitors for patients with SMARCA4‐deficient thoracic tumors." (PMID 38124509, 2023). "This study examines the clinical, pathological, immunohistochemical, and genetic profiles of 36 patients with advanced SMARCA4‐deficient thoracic tumors, focusing on their responses to chemotherapy and immunotherapy." (PMID 38124509, 2023). "Recently, a new category of tumors called SMARCA4-deficient undifferentiated thoracic tumor has been reported." (PMID 33968782, 2021). "SMARCA4-deficient thoracic tumor should be considered in a [18F]FDG-avid aggressive thoracic tumor in heavy smoker men with emphysema." (PMID 34181162, 2021). "SMARCA4-deficient thoracic tumor (SMARCA4-DTT) is a distinct entity of undifferentiated thoracic malignancies newly introduced in 2015." (PMID 34181162, 2021). "Recently, a new category of thoracic tumors has been described, designated as SMARCA4-deficient undifferentiated thoracic tumor (SD-UTT)." (PMID 33937057, 2021). "Thoracic SMARCA4-deficient undifferentiated tumors (SMARCA4-UT) were considered distinct from the traditional NSCLC with SMARCA4-deficient (SMARCA4-dNSCLC) in the 5th edition of the WHO classification of thoracic tumors in 2021." (PMID 42100401, 2026). "Immunohistochemical features of patients with SMARCA4 deficient undifferentiated thoracic tumor." (PMID 40909976, 2025).